IL2 (interleukin 2)
Diseases named in the same sentence as IL2 in open-access papers (continued):
Sharing a sentence is not in itself a finding about the gene and the disease.
tumor (continued). "Further, we found that CD8+PD-1+ T cells expanded in IL-2 were capable of secreting IFN-γ and lysing tumor in vitro." (PMID 35480107, 2022). "The tested candidates induced release of IL-2, granzyme B, perforin, and IFNγ from human PBMC in response to UACC-257 tumor cells." (PMID 35645207, 2022). "Overall, NEO increased the proinflammatory function of tumor-infiltrating CD4+ T cells, with enhanced TNF-α and IL-2 but reduced IL-4 and IL-10 expression." (PMID 36509285, 2022). "Th1 cells can coordinate cytotoxic T lymphocytes and NK cells to exert anti-tumor effects by secreting multiple cytokines (IFN-γ, TNF-α and IL-2)." (PMID 36776357, 2022). "From the concentrations measured in the supernatant, we found that CAR-T cells from all three sources secreted higher levels of IL-2, TNF-α, and IFN-γ than WT T cells after coculture with Nalm6-GL tumor cells." (PMID 35965561, 2022). "Binding to the CAR cognate antigen on the tumor cell induces NFAT phosphorylation, migration to the nucleus and induction of the NFAT-responsive/IL-2 minimal promoter that drives transgene expression." (PMID 36032080, 2022). "After NKG2D(z) and NKG2D(bbz) CAR-T cells were co-cultured with target tumor cells for 96 h, NKG2D(bbz) CAR-T cells exhibited lower exhaustion and secreted more IL2 within 24 h than NKG2D(z) CAR-T cells." (PMID 35965586, 2022). "It is especially worth mentioning that those cell surface receptors are significantly upregulated on NK cells (i.e., CD56, CD94) of NSCLC patients in advanced tumor stages, which are also increased after stimulation with Hsp70-peptide TKD and IL-2." (PMID 36428793, 2022). "In a preclinical study, anti-CEA CAR NK-92MI, an IL-2 independent derived NK-92 cell line, has been demonstrated to recognize and kill CEA-expressing tumor cells at high and moderate levels." (PMID 35891197, 2022). "Activated immune cells, NK cells, in the presence of chemokines such as IL-12, IL-2 and IFN-α/β, metastasize to the tumor area and release IFN-γ, TNF-α and CD107 to exert anti-tumor effects." (PMID 36176401, 2022). "It was associated with increased numbers of NK, CD8+, and CD4+ T cells in addition to increased secretion of anti-tumor cytokines, including IFN-α, IFN-γ, and IL-2." (PMID 35139879, 2022). "Their studies and practices in the IOZK indicated that DCs loaded with the lysate of NDV-infected tumor cells (viral oncolysate, VOL) triggered potent anti-tumor immunity by promoting the secretion of IFN-γ and IL-2 from T-cells." (PMID 36311790, 2022). "Tumor-infiltrating CD8+ T cells activated by ICIs secrete anti-tumor cytokines such as interferon-γ, tumor necrosis factor-α, interleukin-17, and interleukin-2 (IL-2)." (PMID 36139451, 2022). "Thus, IL-2 has the potential to activate tumor-reactive T effector and memory cells and NK cells to induce antitumor immunity, but also Tregs that may limit inflammation, self-reactivity, and anti-tumor responses." (PMID 35651800, 2022). "Two distinct functions of cytokines promoted by T lymphocytes were generated: the first was T helper one (Th1) cytokines mediated by IL-2 and IFN-c and acted to initiate the cell-mediated immunity that played a role in tumor destruction." (PMID 35928372, 2022). "Conversely, interleukin 2 (IL-2) and interferon α (IFN-α) show anti-tumor properties including anti-proliferative and pro-apoptotic activities." (PMID 36005828, 2022). "Structurally similar to interleukin 2 (IL-2), IL-15 supports the persistence of CD8+ memory T cells while inhibiting IL-2-induced T cell death that better maintains long-term anti-tumor immunity." (PMID 35806311, 2022). "To further reveal the relationship between FR4 positive cells and tumor immune microenvironment, we used 90 ESCC data from the TCGA public database to analyze PD-1, PD-L1, IL-2, IL-7, and levels of IFN-γ and TNF-α." (PMID 35756495, 2022). "We also assessed polyclonal IL-2/IFN-γ-producing CD4+ and CD8+ T cells that support anti-tumor immunity." (PMID 36876140, 2022).
tumor (continued). "Our data show that soluble Siglec-5 increased the frequency of IL-2, IFN-γ and TNF-α by MEL624 tumor antigen specific CD4 T cells." (PMID 35290663, 2022). "The bispecific and combination CAR-T cell strategies showed dramatically higher TNF-α, IL-2, and IFN-γ levels than monospecific CAR-T cells upon tumor cell stimulation." (PMID 35317524, 2022). "The immunogenic characteristics of RCC, which are poorly chemosensitive tumours, were first highlighted in the 1990s, with the use of INF-α and IL-2 leading to tumour shrinkage in some metastatic patients." (PMID 36551715, 2022). "Compared with the untreated tumor-bearing mice, the gefitinib-treated mice in the TB-G group expressed markedly lower mRNA levels of NKp46 and CD16 and higher IL-2 mRNA levels." (PMID 36547898, 2022). "The synergistic effect of the TKD/IL-2 on NK cell stimulation, compared to IL-2 alone, has been documented by an increased production of GrB and IFN-γ and interaction with the tumor target cells." (PMID 35720311, 2022). "Many studies have attempted to improve low dose IL-2 therapeutic effect by depleting regulatory T cells, or neutralizing TGF-β or IL-10 with significant, but minor, increases in the anti-tumor response." (PMID 36231109, 2022). "To further understand the observed anti-tumor effects elicited by Salmonella + Alb-IL2 treatment, we characterized the resulting T cells in CT26 tumor-bearing mice treated with single agent or combination therapy." (PMID 35962391, 2022). "Expression of CD137 on NK cells is induced by IL-2 and IL-15, and following CD137 signaling, it promotes NK cell proliferation and production of IFN-γ, which, in turn, can support NK tumor effector functions." (PMID 35880177, 2022). "Stimulation of NK cell by IL-2-generated lymphokine-activated killer (LAK) cells, which shows an increase in cytotoxic potential against tumour cells." (PMID 35628346, 2022). "Synthetic IL-2 production likely enables infiltrating T cells to survive and initiate sustained CAR-mediated activation, expansion and tumor killing." (PMID 36520915, 2022). "IL-18 induced increased expansion of Vδ2 T cells stimulated by ZOL and IL-2, and expanded cells displayed an effector memory phenotype, with high levels of production of IFN-γ, TNF-α and strong cytotoxicity against tumor cells like mesothelioma cells." (PMID 36429001, 2022). "Superior tumor control and improved survival were evident in mice treated with OMCPmutIL-2–expanded CD8+ T cells compared with those expanded by either IL-2 or IL-15." (PMID 35603788, 2022). "Currently, recombinant cytokine drugs such as IL-2 and IFN-α, have been approved for anti-tumor treatment." (PMID 36168626, 2022). "Poly (I:C) treatment significantly increases the IL-2 and IFN-γ production of chimeric antigen receptor-modified T (CAR T) cells along with improving their lytic action against tumor or cancer cells." (PMID 35309296, 2022). "For instance, the upregulation of lnc-TIM3 in tumor-infiltrating CD8 + T cells prevents IFN-γ and IL-2 production and leads to T cell exhaustion in the TME." (PMID 35189921, 2022). "TGF-β released by tumor cells into the TME also decreases the effectiveness of natural killer (NK) and CD8+ T-cells to eliminate cancer cells through the downregulation of interleukin-2 production." (PMID 35626144, 2022). "Neospora caninum treatment significantly increased the mRNA expression levels of IL-12, IFN-γ, IL-2, IL-10, TNF-α, and PD-L1 in the TME, and IL-12 and IFN-γ in the spleen of tumor-bearing mice (P < 0.05)." (PMID 36138417, 2022). "The EpCAM BiTE secreted from infected malignants effectively mediated the binding of EpCAM-positive tumor cells and CD3ε on T cells, which led to activation of naive T-cell and the release of cytokines, such as IFN-γ and IL-2." (PMID 36451817, 2022). "Cells with the synthetic IL-2 circuit autonomously identified the target tumor (CD19+/right) and locally expanded approximately 100-fold within this tumor." (PMID 36520915, 2022).
tumor (continued). "We isolated serum from human PD-1/PD-L1 MC38 tumor allograft-bearing mice treated with Oxa alone, RCE alone, and RCE plus Oxa, and then carried out sandwich ELISA to examine the content of IL-2 and GrB in these different samples." (PMID 36139451, 2022). "Typically, cytokines mattering immune activation and CAR‐T replication (IL‐2, IL‐6, TNF‐α, and IFN‐γ) are drastically increased, hinting at the replication and function maintenance of CAR‐T cells for executing anti‐tumor actions." (PMID 36156442, 2022). "Generally, IL-2, IFN-gamma, IFN-alpha, and TNF-alpha signaling can elicit a pro-inflammatory response and demonstrate potent anti-tumor effects in CRC through a direct and indirect mechanism." (PMID 36362062, 2022). "That being said, the cytotoxicity of patient-derived γδT cells against target tumor cell SH-SY5Y was definitely enhanced in the presence of IL-15 only, compared to those cultured in IL-2 only." (PMID 35351861, 2022). "Co-culture with macrophages treated with tumor exo-NAC or exo-miR-155-5p increased TNF-α, IFN-ɣ, and IL-2 levels in T cells." (PMID 35086548, 2022). "PDAC-infiltrating CD8+ T cells in the NEO cohort produced more IL-2 than corresponding circulating CD8+ T cells and tumor-infiltrating T cells in the PR cohort." (PMID 36509285, 2022). "Tumor-infiltrating cells (TICs) were isolated from the surgically resected tumors and their capacity to produce IFN-γ, TNF-α and IL-2 was examined by FCM." (PMID 35595859, 2022). "CIITA-Exo enhanced the splenocyte proliferation and IL-2 secretion, and induced inflammatory cytokines (such as TNF-α and IL-12) mRNA production, so that CIITA-Exo had a more potent anti-tumor immune response compared to control Exos." (PMID 36733388, 2022). "The expression of VISTA on CD4+ T cells in tumor tissue showed low secretion of cytokines including IFN-γ, IL-2, IL-4, IL-10, IL-17, and IL-12p70." (PMID 35122478, 2022). "We further tested the levels of cytokines in the serum of tumor-bearing mice and found that FAVO increased the serum levels of IL-2 and IFN-γ but reduced the serum level of IL-6." (PMID 35392643, 2022). "The proliferation of CD4+CD25+ Treg cells can be stimulated by inhibitory cytokines, such as IL-10 and TGF-β secreted from tumor cells within the TME, and they directly inhibit the activation of CD8+ effector T cells and restrict their IL-2 production." (PMID 36553542, 2022). "Conus pennaceus-derived anticancer peptides showed antiangiogenic and IL-2-inducing properties with moderate BBB-permeation and were defined to be a tumor-homing peptide (THP) with the ability to inhibit programmed death ligand-1 (PDL-1)." (PMID 36547910, 2022). "More interestingly, we found a greater release of IL-2 and GrB co-cultured with tumor-infiltrating CD3+CD8+ T cells than that co-cultured with tumor-infiltrating CD3+ T cells at the treatment with RCE plus Oxa." (PMID 36139451, 2022). "GSEA analysis of our RNA-seq data from the PSaRC318 tumor at relapse demonstrated upregulation of multiple immunoregulatory pathways including TNFα/NFκB, inflammatory response, TGFβ, IL6, IL2, and IFNγ." (PMID 36187937, 2022). "The mechanism of action of IL-2 is to promote the generation of lymphokine-activated killer (LAK) cells, which are cytotoxic for tumour cells." (PMID 35741162, 2022). "The results showed increased tumor-infiltrating CD8+ T cells, high levels of secreted IL-2 in the TME and enhanced proliferation of tumor-specific cytotoxic T cells improving immunity and facilitating infiltration of activated T cells into HCC tumors." (PMID 36338731, 2022). "To bolster potency, we developed a F i-CAR construct capable of IL-2-mediated, NFAT-induced secretion of anti-PD-1 single-chain variable fragments (scFv) within the tumor microenvironment, following ROR1-mediated activation." (PMID 35659040, 2022).
tumor (continued). "Given that the tumor-infiltrating Pmel-1 was analyzed on day 14, which was 9 days after adoptive transfer, the significant reduction in the PD-1+ proportion by the TBI/IL-2 combination implied insufficient activation." (PMID 36497152, 2022). "The findings demonstrate that the combination of IL-2 and AKK improved tumor suppression in tumorigenic animal models." (PMID 36263037, 2022). "As we know, Th1 cells can produce interferon-γ, interleukin-2, and tumor necrosis factor, which activate macrophages and CD8+T cells to enhance immunity against tumor." (PMID 36505872, 2022). "The polymeric macroparticles successfully co-released IL-2 and anti-CTLA-4 inducing dual effects in activating and promoting tumor antigen-specific T cells." (PMID 35273607, 2022). "As an immunosuppressive microenvironment is favorable for tumor growth and progression, we measured the levels of proinflammatory cytokines (IFN-γ, TNF-α, GM-CSF, and IL-2) and anti-inflammatory cytokines (TGF-β, IL-17, IL-10, and IL-4) within tumors." (PMID 36429032, 2022). "Effector CD8+ T cells can kill tumor cells and secrete several kinds of cytokines, such as IFN‐γ and IL‐2." (PMID 34658167, 2021). "Thus, nowadays, IL-2 should rather be considered an “immune regulatory” cytokine and may be by far less important than previously anticipated for the generation of pro-inflammatory and anti-tumor immune responses." (PMID 33868284, 2021). "In another work aiming to improve the proliferation, homing, and persistence of anti-tumor ACT cells, NKTR-214, a novel IL2Rβγ-biased cytokine, was designed to function as an alternative to conventional IL-2." (PMID 34000441, 2021). "Densitometry analysis showed that five cytokines, IL-4, AXL, IL-1β, IL-9, Exotaxine-2 and IL2, were upregulated, and two cytokines, PF4 and IL-6, were downregulated in the tumor environment of JEG3-Sh-NLRP7 cells." (PMID 34203890, 2021). "Some cytokines, such as IL12 and interleukin 2 (IL2), have great potential in enhancing cytotoxic cellular immunity, which is considered necessary for tumor eradication." (PMID 34766145, 2021). "Importantly, we demonstrated that activation of the NK cells with IL-2 could almost completely restore the NK cell responses, illustrating that IL-2 is a potent activator of NK cells and that NK cells can mediate anti-tumor responses in a hypoxic environment when sufficiently activated." (PMID 34203549, 2021). "With increased tumor PD-L1, expression of activation and cytotoxicity marker genes, including IFNG, TNFSF9, TNFSF14, CSF2, and IL2, were downregulated in both Tnull and TCR-TMART-1, consistent with results of cytokine secretion assays." (PMID 33754038, 2021). "Regulated DC recognizes and phagocytoses tumor cells and induces the release of inflammatory factors such as IFN-γ, IL-2, and TNFα from immune cells." (PMID 34804019, 2021). "Treg cells are involved in tumor progression by explicitly improving the expression of CTLA4; glucocorticoid-induced TNF receptor (GITR); IL-2, IL-10 and IL-35; lymphocyte-activation gene-3 (LAG3); and TGF-β." (PMID 34834282, 2021). "The oncolytic adenovirus TILT-123 co-expresses IL-2 and TNF-α, promotes tumour infiltrating lymphocyte activation and is entering a phase 1 trial for patients with solid tumours (NCT04695327)." (PMID 34888493, 2021). "We also used the ID8 tumor model to evaluate the combinatorial use of OCDC, acetylsalicylic acid, low-dose IL-2 and OC standard-of-care." (PMID 34572778, 2021). "We therefore assessed the production of several effector molecules important for T cell mediated tumor immunity (IFN-γ, GrB, IL-2, IL-17, IL-22, TNF) following polyclonal stimulation with PMA and Ionomycin." (PMID 33885944, 2021).
tumor (continued). "However, the use of several cytokines, such as interleukin-2 (IL-2), interferon α (IFNα) and granulocyte-macrophage colony-stimulating factor (GM-CSF) as adjuvants led to the development of genetically modified whole tumor cell strategies which has increased the efficacy of whole cell vaccines." (PMID 34207062, 2021). "The iPSC vaccine significantly increased CD8+ cytotoxic T cell frequency in the tumor TDLN and promoted T cell activation and antitumor cytokine production (IFN-γ and IL-2) in T lymphocytes, and increased cancer cell-specific antibodies in B cells." (PMID 33961792, 2021). "After migration to the tumour environment, A2AR activation triggers the production of cAMP and the dephosphorylation of STAT5, which abolishes IL-2 and TCR signal-mediated T cell-mediated immune effects." (PMID 34753903, 2021). "Th1 produce type I cytokines, including IL-2 and IFNγ, facilitating optimal expansion, trafficking, and effector functions of CD8+ T cells, thereby reducing tumor growth and progression." (PMID 33535484, 2021). "Analysis of the ID8 OC model revealed a similar trend as in the OC patients whereby animals receiving ASA, low-dose IL-2, OCDC, anti-VEGF antibody (Bev), and Cy (Group C) demonstrated prolonged survival and reduced tumor burden." (PMID 33723260, 2021). "The activation of Vδ1+ cells by TCR engagement combined with cytokine stimulation (i.e., IL-2 or IL-15) upregulates NKRs, correlating with CD56 expression and potent anti-tumour cytotoxicity." (PMID 34944832, 2021). "At 6 hours after therapy on the right side tumor, there was an increase in the levels of IFN-γ and IL-2 in intratumoral CD8 T or NK cells." (PMID 34725216, 2021). "Effector CD8+ cytotoxic and CD4+ helper lymphocytes exert anti-tumor effects upon T-cell receptor (TCR) recognition of antigens and proliferative stimulation by IL-2 protein." (PMID 34084172, 2021). "The cytokine levels of IL-2, IFN-γ, IL-10, and TGF-β1, components that promote antitumor immunity through proinflammatory actions, were found to increase in the serum of tumor-bearing mice following treatment with YFTL." (PMID 34639167, 2021). "Significantly more IFN-γ-expressing CD8+T lymphocytes, elevated levels of IFN-γ and IL-2, fewer CD25+ forkhead box P3 (Foxp3) +Tregs and decreased levels of IL-10 and TGF-β were detected at tumor sites." (PMID 33435564, 2021). "After 24-h co-incubation of tumor cells and effector T cells at an E:T ratio of 10:1, B7-H3 CAR-T cells produced significantly higher amounts of IFN-γ, TNF-α, IL-2, IL-6, IL-4 and IL-10 in the culture supernatants compared with vehicle T cells." (PMID 33514401, 2021). "Here, we investigated the clinical impact of the abundance of resting, IL-2-expanded, and PDGF-DD-activated NK cell phenotypes and the receptors they express in the BLCA tumor microenvironment." (PMID 34858395, 2021). "Consistent with tumor cytokine expression, mice treated with cancer therapeutics and B. bre JCM92 exhibited higher IL-2, STAT5 signaling, and IFN-γ response compared to mice treated with oxaliplatin or PD-1 blockade and B. bre Bb03." (PMID 33668827, 2021). "High levels of interferon (IFN)-γ and interleukin (IL)-2 were recorded 20 h after CAR-T cells, and PC9 tumor cells were co-cultured." (PMID 34553036, 2021). "Th17-like Tregs that expressed IL-17, IL-22, IL-2, TNF and RORγt but in parallel maintained Foxp3 expression markedly enhanced anti-tumor immunity." (PMID 34539668, 2021). "Compared to individual cytokines, one IL12IL2GMCSF fusion molecule can bind to IL12, IL2, or GMCSF receptors, making it much easier to be captured and retained at tumor sites." (PMID 34766145, 2021). "Representative cytokines for the Th1 subset, with classic anti-tumor activity include IFN-γ and IL-2 and the Th1/Th2 ratio is critical for numerous immune responses." (PMID 33669271, 2021).